PAX3 (paired box 3)
Diseases named in the same sentence as PAX3 in open-access papers (continued):
Sharing a sentence is not in itself a finding about the gene and the disease.
preeclampsia (1 paper, 2023). Preeclampsia is a hypertensive disorder of pregnancy that is characterized by new-onset hypertension with proteinuria presenting after 20 weeks of gestation, and depending on mild or severe forms may initially present with severe headache, visual disturbances, and hyperreflexia. "It was also reported that miR-30b-5p reduces Pax3 levels to transcriptionally repress the expression of SLC7A11 to promote the hypoxia-induced ferroptosis of trophoblasts during preeclampsia." (PMID 37686142, 2023).
renal carcinoma (1 paper, 2014). A carcinoma arising from the epithelium of the renal parenchyma or the renal pelvis. "Previous studies have illustrated that Pax3 and Pax7 are associated with cell survival in numerous cancer cell lines and silencing of pax2 promotes renal carcinoma apoptosis." (PMID 25197636, 2014).
sarcomatoid carcinoma (1 paper, 2011). A malignant epithelial neoplasm characterized by the presence of spindle cells and anaplastic morphologic features. "If the tumor is negative for PAX3 or 7-FKHR translocation and lack of morphologic pleomorphism, most of rhabdomyosarcomatous tumors arising from adult bladder are likely of rhabdomyosarcomatous carcinoma, a form of sarcomatoid carcinoma." (PMID 21762516, 2011).
sarcopenia (1 paper, 2013). Progressive decline in muscle mass due to aging which results in decreased functional capacity of muscles. "We hypothesize that paired-box transcription factors, Pax3/7, are involved with this enhanced self-renewal and that prolonged expression of these factors may allow some fish species to escape, or at least forestall, sarcopenia/dynapenia." (PMID 23967015, 2013).
Sjögren’s syndrome (1 paper, 2023). "The Pax3 gene variant has been linked to congenital orofacial defect, and its reduced expression has been associated with Sjögren’s syndrome." (PMID 37759439, 2023).
skin aging (1 paper, 2021). The gradual irreversible changes in structure of skin that occur as a result of the passage of time.. "In the next core pathway of both middle-aged and elderly skin aging, the ligand KITLG promotes melanin synthesis, DNA damage, and inhibits cell-cycle arrest by modulating TFs AR and MITF via signaling transduction proteins FAM83H, HSPB1, PAX3, ATF5, and H2AFB2." (PMID 34073305, 2021).
teratoma (1 paper, 2020). A non-seminomatous germ cell tumor characterized by the presence of various tissues which correspond to the different germinal layers (endoderm, mesoderm, and ectoderm). "The level of mRNAs encoding Pax3 was significantly higher, while the expression of Nfix, Eno3, Mck, Mef2a, and Itga7 was significantly lower in Pax7−/− teratomas, as compared to Pax7+/+ teratomas." (PMID 32552916, 2020). "The level of mRNAs encoding Pax3 was significantly higher, while the expression of Nfix, Eno3, Mck, Mef2a, and Itga7 was significantly lower in Pax7−/− teratomas, as compared to Pax7+/+ ones." (PMID 32552916, 2020). "Pax3 level was slightly higher and Myogenin level was slightly lower in Pax7−/− teratomas than in Pax7+/+ teratomas." (PMID 32552916, 2020).
thyroid (1 paper, 2016). "Our results are consistent with a model, in which PAX3 inhibits thyroid tumorigenesis by inducing cell cycle arrest and apoptosis, and suppressing tumor metastasis through blocking the PI3K/Akt and MAPK pathways and promoting FOXO3a activity." (PMID 27458157, 2016). "Given the importance of PI3K/Akt and MAPK/Erk pathways in thyroid tumorigenesis, we thus tested the effect of ectopic expression of PAX3 on the activities of these two pathways." (PMID 27458157, 2016). "The aim of this study was to explore the functions and related molecular mechanism of PAX3 in thyroid tumorigenesis." (PMID 27458157, 2016). "We first examined mRNA expression of PAX3 in 17 primary PTCs and matched non-cancerous thyroid tissues (control subjects) by using qRT-PCR approach." (PMID 27458157, 2016).
uveal melanoma (1 paper, 2023). A melanoma derived from melanocytes of the uveal tract. "Importantly, analyses of TCGA data confirmed that high expression of PAX3, SOX10, MITF and TFAP2A are defining features of uveal melanoma patient samples and such TFs have been validated as selective cancer dependencies in UM cell lines by large-scale functional genomics screens." (PMID 37400441, 2023).
Wilms' tumours (1 paper, 2019). "Cluster 2 showed expression of the nephron progenitor markers SIX1, SIX2 and CITED1, as well as the stromal marker PAX3 that has previously been associated with myogenic Wilms' tumours." (PMID 30846463, 2019).
tumor (121 papers, 2001 to 2026). "As such, using in vitro and in vivo CAR-T based approaches, FGFR4 has been targeted causing specific cytotoxicity in vitro and decreased tumor burden in vivo in an intramuscular PAX3::FOXO1 xenograft model." (PMID 40599857, 2025). "Pre-treatment samples showed a tumour-specific variant in 14/18 patients, including PAX3::FOXO1 fusion in 10/18." (PMID 39797974, 2025). "We previously demonstrated weak Pax3::Foxo1 RNA expression in Pax7 CreER tumours with the Pax3::Foxo1 knock‐in allele compared to much higher Pax3::Foxo1 expression in tumours forming after Pax3::Foxo1 was knocked into the other lineages." (PMID 39812007, 2025). "Based on their genotypes, we identified n = 23 tumours corresponding to the ML cluster (Pax3::Foxo1 in Myf5, Myf6, or Pax3 lineage) and n = 33 tumours corresponding to the MR cluster (other mutations in any lineage or Pax3::Foxo1 in Pax7 lineage)." (PMID 39812007, 2025). "Both mutational changes (expression of the Pax3::Foxo1 fusion protein) and cell of origin (specific myogenic lineage in which the tumour developed) were identified as important factors contributing to the DNA methylation pattern of these tumours." (PMID 39812007, 2025). "Using RMS tumours arising in these GEMMs, our study demonstrates a strong association between Pax3::Foxo1 expression and DNA methylation pattern." (PMID 39812007, 2025). "The PAX3 gene has been associated with documented tumour regressions, possibly involved in a regulatory pathway, slowing tumour growth." (PMID 37255207, 2023). "In univariate analysis, age over 10 years and tumor expression of a PAX3/PAX7-FOXO1 FT were significant risk factors of event (p = 0.048 and p = 0.004, respectively)." (PMID 35186818, 2021). "Elevated circulating miR-658 was associated with tumor metastasis through activation of the PAX3-MET pathway." (PMID 32368305, 2020). "The gene expression microarrays studies revealed that neurogenesis-associated genes are differentially expressed when tumours are evaluated according to the PAX3/7-FOXO1 fusion status." (PMID 31493794, 2019). "Positive reaction with OLIG2 (6 tumours) was always associated with the presence of PAX3/7-FOXO1 rearrangement." (PMID 31493794, 2019). "Molecular analysis of the tumor cells revealed a PAX3-FKHR (paired box 3 - forkhead box O1) translocation that is usually associated with very poor outcome (3-year event-free survival < 10%)." (PMID 21843360, 2011). "Therefore, in RMS both TFAP2B and ALK are functionally linked to PAX3/7-FOXO1 fusion positive tumours." (PMID 31493794, 2019). "Importantly, EphB4 receptor tyrosine kinase signaling has been associated with oncogenic Pax3:Foxo1 fusion protein expression and involved in aRMS tumor progression." (PMID 28817624, 2017). "Thus, it remains to be seen whether they are the natural cooperating partners of PAX3-FKHR or are acquired as secondary mutations during later stages of tumor evolution." (PMID 23799156, 2013).
tumor (continued). "The correlation of PAX3::FOXO1 with inferior OS decreased; however, when associated with other adverse prognostic factors such as large tumor size and older age." (PMID 39781573, 2025). "Hippo signaling is suppressed in alveolar RMS cell lines and tumors, and genetically inhibiting the Hippo/MST signaling by knocking out kinases MST1 and MST2 (Stk4, Stk3), led to more rapid Pax3::Foxo1 tumor onset and higher penetrance." (PMID 40599857, 2025). "In the zebrafish PAX3::FOXO1 tumor model, the effect of many promoters/restricted cell lineages was investigated to understand transformation capacity on a broader scale." (PMID 40599857, 2025). "Although there is cell cycle regulation of Pax3::Foxo1 expression resulting in intercellular heterogeneity within these mouse FP RMS tumours, our results suggest that the overall long‐term Pax3::Foxo1 expression pattern contributes to DNA methylation." (PMID 39812007, 2025). "This latter finding can be explained by the very low expression of Pax3::Foxo1 in these Pax7 lineage tumours, resulting in an inadequate amount of Pax3::Foxo1 to modulate the epigenetic landscape in this setting." (PMID 39812007, 2025). "Using this PAX3::FOXO1 zebrafish tumor model, this group also identified a novel PAX3::FOXO1 target gene her3, the human ortholog HES3, that is upregulated in fusion positive RMS patients." (PMID 40599857, 2025). "Age, IRS group, tumor size, site and invasiveness, nodal status and fusion type (PAX7:: vs. PAX3::FOXO1) were significantly associated with OS." (PMID 39781573, 2025). "Multivariate analysis of the COG cohort identified older age (≥10 years) and tumor size >5 cm as independent adverse prognostic factors for EFS, and for OS in addition to tumor size, tumor invasiveness (T2) and PAX3::FOXO1 variant." (PMID 39781573, 2025). "As only one tumour arose in the setting of Pax3::Foxo1 directed to the Myf5 lineage, which is often embryonic lethal, the usual impact of Pax3::Foxo1 on DNA methylation in this lineage is unclear." (PMID 39812007, 2025). "These tumours possess a lower mutational rate, although a translocation is found in 80% of ARMS tumours, which results in PAX3/7-FOXO1 fusion protein formation." (PMID 38473371, 2024). "For evaluation of entinostat monotherapy, models CTG-1008 and CTG-1916 had no single agent activity in line with previously-published studies showing that PAX3::FOXO1 is dispensable for tumor maintenance in the short term." (PMID 39147820, 2024). "To date, one group has discovered a PAX3::FOXO1 breakpoint peptide capable of inducing circulating T lymphocytes to lyse tumor cells." (PMID 38473380, 2024). "Despite PAX3::FOXO1 being dispensable in the short turn to tumor cell growth, PAX3::FOXO1 is nonetheless critical to mediate a G2-specific, Survivin/IAP-mediated process of chemotherapy resistance called cell cycle checkpoint adaptation." (PMID 39147820, 2024). "The elevated presence of miR-206 induces myogenic differentiation and impedes tumor growth by targeting essential genes like c-Met, PAX3, and G6PD." (PMID 38826780, 2024). "One limitation of this study is that previous work showed that expression of PAX3/7-FOXO1 alone is insufficient to induce tumor formation in most cell types, and requires the additional loss of a tumor suppressor." (PMID 39902277, 2024). "Isolated tumor cells with lower Pax3::Foxo1 expression had a higher oncogenic capability in allograft models and more migratory potential in vitro, a phenomenon that is also seen for the EWSR1::FLI1 fusion in Ewing sarcoma." (PMID 38916046, 2024). "By suppressing the expression of c-Met and PAX3, miR-1 also acts as a tumor suppressor, resulting in cell cycle arrest and autophagic cell death." (PMID 38826780, 2024). "In this model, the human VGLL2::NCOA2 coding sequence was incorporated into the zebrafish genome under the ubiquitous CMV promoter using a similar approach to the PAX3::FOXO1-driven zebrafish tumor model." (PMID 38916046, 2024).
tumor (continued). "Expression of PAX3::FOXO1 in a regulatable myoblast model causes colony formation in vitro and tumor formation in vivo, while reduced fusion protein expression inhibits both phenotypes." (PMID 37732905, 2023). "APC/C (Cdh1) has a tumor suppressor function in melanocytes mediated by the subunit Cdh1, which inactivates PAX3 through ubiquitination and degradation, implying consequent inhibition of MITF production." (PMID 36274944, 2022). "One the one hand, it has been documented that the PAX3/7–FOXO1 fusion in RMS tumor cells results in constitutively active mTOR signaling." (PMID 34205996, 2021). "In this study, we have assumed that miR-299-3p acts as a tumor suppressor during GC cell growth by base-pairing the target gene PAX3." (PMID 33817318, 2021). "Because genes expression profiles are specific for molecular subtypes of tumours, they can be explored for identification of tumours with PAX3/7-FOXO1 fusions." (PMID 31493794, 2019). "The oncogenic role of PAX3 has also been investigated in many different tumor entities including melanoma, resulting in a potential involvement of this gene in tumor progression." (PMID 31118886, 2019). "ENT, a potent and selective Class I HDAC inhibitor, reduced the abundance of the tumor-driving PAX3:FOXO1 mRNA and protein expression." (PMID 31113472, 2019). "This fusion transcription factor dysregulates PAX3 target genes resulting in gene expression changes that modify pathways involved in proliferation and/or survival, contributing to tumour initiation." (PMID 28615069, 2017). "Chromatin immunoprecipitation and NNMT promoter luciferase assays revealed that AURKA’s effects on NNMT were caused by PAX3-mediated transcriptional repression and overexpression of NNMT blocked tumor cell invasion in vitro." (PMID 28102366, 2017). "Together, these data suggest that the PAX3 promoter engages in interactions with potential FOXO1 regulatory elements in the translocated chromosome in ARMS tumours, interactions that are restricted to the wild-type 3' TAD border of the FOXO1 locus." (PMID 28615069, 2017). "Given that EMT is a biological process inducing migratory and invasive capabilities and promoting tumor metastasis, we thus attempted to clarify the correlation between PAX3 and the EMT process in this study." (PMID 27458157, 2016). "By exploring the expression of the competing triplets H19-miR-206-PAX3, we also found that the correlations between miR-206 with the two ceRNAs (H19 and PAX3) were all positive in normal and tumor states." (PMID 27580177, 2016). "With sequential morphoproteomic profiling on such a case in conjunction with personalized tumor graft testing, we provide an expanded definition of the biology of PAX3-FKHR (FOXO1) ARMS that integrates genomics, proteomics and pharmacogenomics." (PMID 27323832, 2016). "This was reflected in PAX3, MITF, as well as MITF target gene expression, demonstrating that reduced MITF function is linked to repressed tumor growth." (PMID 26977879, 2016). "Tumor induced by PAX3-transfected FTC133 cells showed significantly longer latency and smaller mean tumor volume than tumors induced by control cells." (PMID 27458157, 2016). "Given in vitro growth-inhibitory activity of PAX3, we next assessed the impact of PAX3 re-expression on tumor growth in nude mice." (PMID 27458157, 2016). "Mechanically, PAX3 exerted its tumor suppressor function by inhibiting the activity of major signaling pathways including the phosphatidylinositol-3-kinase (PI3K)/Akt and MAPK/Erk pathways, and enhancing expression and activity of transcription factor FOXO3a." (PMID 27458157, 2016).